TBC1D16 (TBC1 domain family member 16)
Description:
May act as a GTPase-activating protein for Rab family protein(s).
Synonyms: MGC25062; FLJ20748
Tractability: PROTAC: ubiquitination databases record sites on it; its protein half-life has been measured.
Gene: Protein-coding gene on chromosome 17 (79,932,343 to 80,035,877, reverse strand). Ensembl gene ENSG00000167291.
Subcellular location (Human Protein Atlas): Intermediate filaments
Pathways (Reactome):
Vesicle-mediated transport: TBC/RABGAPs
Gene Ontology:
Molecular function: GTPase activator activity; protein binding
Biological process: regulation of cilium assembly; regulation of receptor recycling
Cellular component: cytosol; early endosome
Genetic constraint (gnomAD): Loss-of-function variants: 60 observed, 71.63 expected, observed/expected ratio (o/e) 0.84, 90% interval 0.68 to 1.04. The upper end of that interval is the gene's LOEUF score, 1.04, which puts it in group 4 of 6, group 1 being the genes least tolerant of losing a copy. Missense variants: 1,014 observed, 1,049.4 expected, observed/expected ratio (o/e) 0.97, 90% interval 0.92 to 1.02. Synonymous variants: 493 observed, 457.94 expected, observed/expected ratio (o/e) 1.08, 90% interval 1 to 1.16.
Homologues: Orthologues: chimpanzee TBC1D16 (99% identical), macaque TBC1D16 (98% identical), mouse Tbc1d16 (89% identical), rat Tbc1d16 (88% identical), dog TBC1D16 (87% identical), guinea pig TBC1D16 (87% identical), tropical clawed frog tbc1d16 (71% identical), zebrafish tbc1d16 (68% identical), rabbit TBC1D16 (59% identical), Drosophila melanogaster TBC1D16 (41% identical), Caenorhabditis elegans tbc-16 (36% identical). Paralogues in human: TBC1D10B (15% identical), TBC1D25 (15% identical), TBC1D4 (15% identical), TBC1D17 (15% identical), TBC1D1 (15% identical), TBC1D15 (14% identical), TBC1D9 (14% identical), TBC1D9B (14% identical), RABGAP1 (14% identical), TBC1D8 (14% identical), RABGAP1L (14% identical), TBC1D2 (13% identical), and 33 more.
Diseases named in the same sentence as TBC1D16 in open-access papers:
TBC1D16 is named in the same sentence as 32 diseases in open-access papers, as found by Europe PMC text mining. Sharing a sentence is not in itself a finding about the gene and the disease. The quoted sentences say what the papers report.
melanoma (17 papers, 2012 to 2025). A malignant, usually aggressive tumor composed of atypical, neoplastic melanocytes. "In cancer, particularly melanoma, TBC1D16 has been associated with tumor progression due to its role in promoting cell proliferation, migration, and invasion." (PMID 39712483, 2024). "Elevated TBC1D16 expression has been linked to poor prognosis in melanoma patients, suggesting its potential as a prognostic biomarker." (PMID 39712483, 2024). "Several CpG sites in the gene body of TBC1D16, including the TBC1D16-47KD cryptic promoter, exhibited significant loss of methylation (− 47% on average) in metastatic melanomas (green and magenta boxplots) compared to primary tumours (red boxplots)." (PMID 31383000, 2019). "TBC1D16 is also highly associated with the development of cancer due to hypomethylation in intron 5 of the gene that has been shown to reactivate a small transcript of TBC1D16 (TBC1D16-47KD), which exacerbates melanoma growth and metastasis." (PMID 31921306, 2019). "The overexpression of the Rab GTPase-activating protein TBC1D16 (47KD short isoform) in primary tumor cells can enhance melanoma progression by targeting EGF-stimulated EGFR degradation mediated by RAB4A." (PMID 41155412, 2025). "Functional experiments indicated that TBC1D16 significantly impacts the migration and proliferation of melanoma cells." (PMID 39712483, 2024). "Studies indicate that silencing TBC1D16 can reduce melanoma cell migration and proliferation, highlighting its significance in tumor aggressiveness and as a potential therapeutic target." (PMID 39712483, 2024). "By silencing TBC1D16, we demonstrated a significant reduction in the migratory potential of melanoma cells, indicating its potential as a target for novel therapies aimed at limiting metastasis." (PMID 39712483, 2024). "First, we found that DNA hypomethylation enhances the expression of a cryptic transcript of Rab GTPase‐activating protein TBC1D16 (TBC1D16-47KD), a short isoform that exacerbates melanoma growth and metastasis." (PMID 37369946, 2023). "TBC1D16 also appears to be the driving gene in melanoma, and its overexpression can promote cell growth and gene expression, affecting vesicle transport and further influencing melanoma progression." (PMID 35918393, 2022). "Hypomethylation of TBC1D16 leads to the activation of TBC1D16 transcription in melanoma, and the short isoform of TBC1D16 (TBC1D16-47KDa) promotes melanoma growth and metastasis through interacting with RAB5C and regulating EGFR signaling." (PMID 33194704, 2020). "Seven prognosis associated TBCs genes including TBC1D13, TBC1D16, TBC1D7, TBC1D10C, TBC1D19, TBC1D8B, and TBC1D15 were identified in melanoma." (PMID 33194704, 2020). "As reported in the literature, TBC1D16 as a driver of melanoma is a Rab4A GAP that is engaged in the trafficking of transferrin receptor and EGFR." (PMID 33194704, 2020). "Loss of TBC1D16 methylation was associated with activation of an alternative cryptic transcript, TBC1D16-47KD, which was shown to promote melanoma proliferation and metastasis." (PMID 31383000, 2019). "Hypomethylation of TBC1D16 was previously reported in metastatic vs primary melanoma, breast cancer and other tumour types." (PMID 31383000, 2019). "Expression of FAM174B, MAD1L1, SCARB1, MFSD12, SEMA6A, SLC45A2, and TBC1D16 was found to be upregulated and associated with worse OS in melanoma patients, while only MFSD12 and SLC45A2 were associated with worse DFS for melanoma patients." (PMID 30385854, 2019). "Further in vitro and in vivo functional analyses indicated that TBC1D16-47KD promoted melanoma proliferation and metastasis, possibly by regulating Rab GTPases and EGFR activation." (PMID 31383000, 2019). "We also evaluated methylation of TBC1D16 CpG sites (at chr17: 77924371–77925136, GRCh37; cg18749563, cg07618085, cg17295878, cg23651872 and cg19004465) in the same melanoma dataset (right)." (PMID 31383000, 2019).
melanoma (continued). "A comprehensive DNA methylation study of melanomas at various stages of development identified some genes specifically involved in tumor development (HOXA9) or progression (TBC1D16)." (PMID 29156643, 2017). "In support of this, one of the members of our gene signature, TBC1D16, has recently been shown to be involved in the metastatic cascade of melanoma." (PMID 28578692, 2017). "They applied the proposed method to a melanoma data set and identified known driver genes in melanoma, along with novel cancer driver genes TBC1D16 and RAB27A." (PMID 23940583, 2013). "Rab proteins also belong to this family and TBC1D16, encoding Rab3-GAP, has recently been identified as a driver oncogene in melanoma." (PMID 22292074, 2012). "Furthermore, our functional assays targeting TBC1D16 provide compelling evidence for its role in melanoma cell proliferation and migration." (PMID 39712483, 2024). "Bioinformatics analysis showed that TBC1D16 was a melanoma driver gene and could promote the development of melanoma cells." (PMID 39439452, 2024). "TBC1D16 is identified as a driver of melanoma and promotes the growth of melanoma cells." (PMID 33194704, 2020). "Furthermore, they identified three CpGs in TBC1D16 that showed a significant decrease in methylation in metastases compared to primary melanoma." (PMID 31383000, 2019). "TBC1D16 encodes the protein TBC1 Domain Family, Member 16, which is up-regulated in melanoma." (PMID 25387527, 2014). "Protein expression of TBC1D10C, TBC1D19, TBC1D16, and TBC1D13 were increased significantly in melanoma tissues." (PMID 33194704, 2020). "Hypomethylation of TBC1D16 was also shown to increase sensitivity to BRAF and MEK inhibitors but predicted poorer clinical outcome for melanoma patients." (PMID 31383000, 2019). "In one study, researchers identified and validated biomarkers for melanoma development (HOXA9 DNA methylation) and tumor progression (TBC1D16 DNA methylation)." (PMID 31395792, 2019). "We identified and validated biomarkers for, and pathways involved in, melanoma development (e.g., HOXA9 DNA methylation) and tumor progression (e.g., TBC1D16 DNA methylation)." (PMID 28578692, 2017). "Network and/or module based approaches also proved to be powerful in pinpointing disease causing genes, many of which, for example Ppm1l for metabolic syndrome or TBC1D16 and RAB27A for melanoma, have been confirmed experimentally while others are supported by literature evidences." (PMID 23755063, 2012). "No major differences were observed for methylation in TBC1D16, except in a primary and metastatic melanoma cell line pair and a primary melanoma cell line, which exhibited hypermethylation in both the TBC1D16 gene body and TBC1D16-47KD cryptic promoter regions." (PMID 31383000, 2019). "In addition, hypomethylation of TBC1D16 was observed in multiple tumours, including a breast cancer primary/metastasis pair, and to a lesser degree in melanoma, although again not all tumours or cancer primary/metastasis pairs exhibited altered patterns of methylation." (PMID 31383000, 2019).
cutaneous melanoma (4 papers, 2017 to 2024). A primary melanoma arising from atypical melanocytes in the skin. "Among these, TBC1D16 exhibits the strongest positive correlation with the model’s risk score, indicating that it is most closely associated with poor prognosis in patients with skin melanoma." (PMID 39712483, 2024). "Our experiments demonstrated that knockdown of TBC1D16 resulted in a significant decrease in both proliferation and migration capabilities of skin melanoma cells." (PMID 39712483, 2024). "AC100791.3 is antisense to TBC1D16 according to GeneCards, with the protein TBC1D16 playing a critical role in the progression of cutaneous melanoma." (PMID 34426753, 2021).
Obesity (4 papers, 2019 to 2025). Accumulation of substantial excess body fat. "Another candidate gene in Finland, TBC1D16, plays a role in membrane trafficking and molecule transport and is known to be dysregulated in obesity." (PMID 40597625, 2025). "Previous studies have demonstrated that TBC1D16 was involved in various types of diseases, such as high systolic blood pressure, obesity and cancer." (PMID 34367131, 2021). "For example, the interleukin-6 receptor (IL-6R) is linked to increased risk of asthma and obesity, and its expression is positively associated with expression of TBC1D8 and negatively with expression of TBC1D16." (PMID 34301314, 2021). "Three of the four identified genes, TBC1D16, TBC1D8, and RASA2, have been previously implicated in relation to asthma and/or obesity/BMI, supporting the informativity of genes identified in this study." (PMID 34301314, 2021). "Given that TBC1D16 is involved in the canonical PI3K/AKT pathway, which is found deregulated in both obesity and cancer, the activation of TBC1D16-47KD might be one of the links between obesity and cancer." (PMID 31921306, 2019).
colorectal cancer (3 papers, 2019 to 2024). A primary or metastatic malignant neoplasm that affects the colon or rectum. "Further experiments verify the function of the super enhancers governing PHF19 and TBC1D16 in regulating colorectal cancer tumorigenesis, and KLF3 is identified as an oncogenic transcription factor in colorectal cancer." (PMID 34737287, 2021). "In both prostate and colorectal cancers, we observed hypermethylation of TBC1D16 compared to normal prostate tissues and normal colon tissues, respectively." (PMID 31383000, 2019). "Via motif and core regulatory circuitry analysis, multiple important transcription factors in colorectal cancer were predicted, with PHF19, TBC1D16 and KLF3 having a special role to play in colorectal cancer carcinogenesis." (PMID 38542080, 2024). "We also evaluated methylation changes of EBF3 and TBC1D16 in 450k methylation array and RRBS datasets of colorectal cancer." (PMID 31383000, 2019). "However, no discernable methylation differences of TBC1D16 were observed in a colorectal cancer primary/metastasis pair." (PMID 31383000, 2019).
metastatic melanoma (2 papers, 2019 to 2023). A melanoma that has spread from its primary site to another anatomic site. "Characteristic DNA methylation differences have been identified between primary and metastatic melanomas at EBF3 and/or TBC1D16 gene loci." (PMID 31383000, 2019).
metastatic tumors (2 papers, 2017 to 2019). "In metastatic tumors, site-specific hypomethylation was associated with reactivation of a cryptic transcript of TBC1 Domain Family Member 16 (TBC1D16) and poor clinical outcome." (PMID 28030832, 2017).
adenoma (1 paper, 2019). A neoplasm arising from the epithelium. "Almost all analysed CpG sites in EBF3 and TBC1D16 were significantly differentially methylated (− 14% in the gene body of EBF3 and + 9% in the gene body of TBC1D16) in both adenomas and carcinomas compared to normal colon tissue (red vs blue and green vs blue boxplots, respectively)." (PMID 31383000, 2019).
endometrial cancer (1 paper, 2019). Primary or metastatic malignant neoplasm involving the endometrium (mucous membrane that lines the endometrial cavity). "In endometrial cancer, CpG sites in the gene bodies of EBF3 (cg09649486, cg25866634) and TBC1D16 (cg07618085) were significantly differentially methylated (+ 17% and − 14%, respectively) in lymph node metastases compared to primary tumours (green vs red boxplots)." (PMID 31383000, 2019).
latent infection (1 paper, 2021). "We speculated that TBC1D16 might restrict PFV replication by affecting the IFN response induced by PFV, thereby promoting the latent infection of PFV." (PMID 34367131, 2021). "This study revealed that TBC1D16 may be a novel negative factor act as inhibiting PFV replication, providing new insights into the understanding of PFV latent infection." (PMID 34367131, 2021). "However, the mechanism of latent infection of PFV remains unclear and the effect of TBC1D16 on regulating PFV latency has not been investigated so far." (PMID 34367131, 2021).
metastatic cancers (1 paper, 2019). A carcinoma which has spread from the original site of growth to another anatomic site. "Molecular signatures of these circulating tumour cells (CTCs), such as the methylation status of EBF3 and TBC1D16, could potentially be used as a biomarker to help determine the prognosis of metastatic cancers." (PMID 31383000, 2019).
prostate carcinoma (1 paper, 2019). A carcinoma that arises from epithelial cells of the prostate gland. "In prostate cancer metastases significant hypermethylation of one EBF3 (cg03774288) gene body CpG and four TBC1D16 (cg07618085, cg17295878, cg23651872, cg19004465) CpG sites (both + 16%) were observed compared to normal prostate tissue (red vs blue boxplots)." (PMID 31383000, 2019).
tumor (9 papers, 2017 to 2024). "The present findings suggest that methylation changes in EBF3 and TBC1D16, similar to those reported previously, are found in multiple different tumour types and are associated with aggressive tumour behaviour." (PMID 31383000, 2019). "We show here that in several cancer types, characteristic methylation changes in both EBF3 and TBC1D16 were associated with tumour metastasis, which is responsible for the majority of cancer-related deaths." (PMID 31383000, 2019). "In the present study, we have investigated DNA methylation changes in EBF3 and TBC1D16 in publicly available data of multiple different tumour types, so as to further evaluate the potential role of these two genes associated with tumourigenesis and metastasis." (PMID 31383000, 2019). "Furthermore, we detected the mRNA expression level of these hub genes in our frozen tissues and found that FAM174B, MAD1L1, MFSD12, SLC45A2, and TBC1D16 were significantly upregulated in freshly frozen tumor tissues." (PMID 30385854, 2019). "To further evaluate whether these epigenetic changes may act more generally as drivers of tumour onset and metastasis, we have investigated DNA methylation changes involving EBF3 and TBC1D16 in additional publicly available data of multiple different tumour types." (PMID 31383000, 2019). "However, epigenetic changes in EBF3, or TBC1D16, were not identified in all tumour samples, or in all primary/metastasis cancer pairs." (PMID 31383000, 2019).
cancer (5 papers, 2019 to 2024). A tumor composed of atypical neoplastic, often pleomorphic cells that invade other tissues. "Furthermore, Gene Ontology (GO) and Kyoto Encyclopedia of Genes and Genomes (KEGG) enrichment analyses revealed that TBC1D16 is associated with various cancer functions and pathways." (PMID 39712483, 2024). "Gene Set Enrichment Analysis (GSEA) further indicated that TBC1D16 is highly correlated with several cancer-related pathways, including oxidative phosphorylation and Myc target pathways." (PMID 39712483, 2024). "Overall, the findings presented strengthen the view that methylation changes in EBF3 and TBC1D16 are potential epi-drivers of aggressive tumourigenic changes in multiple cancer types." (PMID 31383000, 2019). "Several isoforms of human TBC1D16 have been identified and annotated, and one smaller isoforms (47 kDa) encoded by an alternative transcription start site (TSS) in intron 5 has been shown to be expressed in human cancer cell lines." (PMID 31921306, 2019).
TBC1D16 also shares sentences with these, for which no sentence is quoted: adenocarcinoma of the lung (2 papers); asthma (1); breast carcinoma (1); breast invasive carcinoma (1); Chagas disease (1); chordoma (1); colon adenocarcinoma (1); glioblastoma multiforme (1); glioma (1); metabolic syndrome (1); Parkinson disease (1); Parkinson’s (1); rectum adenocarcinoma (1); small cell lung carcinoma (1); squamous cell carcinoma of the lung (1); stomach adenocarcinoma (1); triple-negative breast carcinoma (1); urothelial bladder carcinoma (1); uterine corpus endometrial carcinoma (1).